TNF (tumor necrosis factor)
Diseases named in the same sentence as TNF in open-access papers (continued):
Sharing a sentence is not in itself a finding about the gene and the disease.
emphysema (continued). "This was made evident by inhibition of TNF-α using a receptor knockout model (TNFR KO), which attenuated the development of emphysema by 71–83% and of SAR by 100% in mainstream cigarette smoke exposure." (PMID 23720629, 2013). "Overexpression of other mediators in the lungs, such as tumor necrosis factor-alpha (TNF-α) and transforming growth factor-beta (TGF-β), has also generated this complex phenotype of fibrosis and emphysema in research animals." (PMID 22448331, 2012). "Leptin was positively related to TNF-α on D1 of the exacerbation and this correlation also applied to both subgroups of COPD patients, thus chronic bronchitis and emphysema." (PMID 19344528, 2009). "In the PPE-instillation emphysema animal model, there is a substantial inflammatory response (MMP and TNF-α) accompanied by an increase in cellular apoptosis and down-regulation of VEGF levels, which are all relevant pathologic characteristics of COPD." (PMID 19930612, 2009). "TNF-α and soluble TNF receptor levels are increased in the sputa of emphysema patients." (PMID 41007683, 2025). "TNF-α and IFN-γ, which are predominantly produced by activated macrophages and lymphocytes, can trigger the release of CXCL10, a chemokine attracting monocytes, neutrophils, and T-cells, notably Th1 cells, thereby contributing to pulmonary emphysema." (PMID 38786103, 2024). "iNOS, an enzyme involved in the macrophage inflammatory response and upregulated by hypoxia or proinflammatory cytokines, such as tumor necrosis factor-α (TNF-α), interleukin 6 (IL-6), or interferon-γ (IFN-γ), plays a crucial role in the development of tobacco smoke–induced emphysema and PH in mice." (PMID 37581311, 2023). "In conclusion, we found an independent relationship between TNFα and IL-1β and radiographic emphysema in PLWH, suggesting that systemic inflammation may be involved in the pathogenesis of emphysema." (PMID 33936110, 2021). "Salidroside treatment decreased emphysema, significantly ameliorated lung function, increased antioxidant, but reduced MDA, IL-6 and TNF-α levels in serum and GN tissues of rats, accompanied by decreased myostain, but increased myogenin expression in GN tissues." (PMID 31702007, 2019). "In the pathological process of airway remodeling and emphysema formation in COPD, macrophages, monocytes, neutrophils, other immune cells, neutrophil elastase, matrix metalloproteinases, interleukins and tumor necrosis factor-α, and other cytokines are involved." (PMID 31143784, 2019). "The finding that our model does not progress to a fibrotic or emphysema-like phenotype contrasts with studies performed in mice overexpressing TNF driven from the surfactant protein C promoter (SP-C/TNF-Tg) restricting expression to the lung." (PMID 29320550, 2018). "Overexpression of TNF-α results in severe PAH and emphysema in mice." (PMID 29861433, 2018). "IL-1β, IL-6, IL-8, and TNFα have all been found to be elevated in COPD and in experimental settings have been found to contribute to the development of persistent airway inflammation, emphysema, and mucus production." (PMID 23533311, 2013). "TNFα was found to drive most of the emphysema development in mice after smoking because mice lacking receptors for TNFα only developed mild emphysema." (PMID 23533311, 2013). "Another animal study demonstrated that simvastatin used in emphysema, reduced mRNA expression of IFN-γ, TNF-α and MMP-12 in the whole lung and reduced the number of neutrophils and lymphocytes and the concentration of TNF-α in BAL fluid, thus reduced inflammation and remodeling." (PMID 24250526, 2012). "Notably, the knockout of HAVCR2 further promotes the infiltration of CD4+ T cells and the expression of IFN-γ in the lungs, resulting in a more severe emphysema phenotype, although it does not significantly affect TNF-α expression." (PMID 39555065, 2024).
emphysema (continued). "The proinflammatory cytokines IL-6 and TNFα have been reported to increase, following exposure to cigarette smoke and WPS, and to play a significant role in the acute smoke-induced inflammatory reaction in the lung, occasioning connective tissue damage which ultimately leads to emphysema." (PMID 32025277, 2020). "Importantly, the mRNA levels of IL-1β, TNF-α, IL-8, IRF-5, IL-18, IFN-γ, TGF-β, matrix metalloproteinase-9 (MMP-9), and MMP-12 were decreased in the FMT-treated emphysema group compared with the emphysema group." (PMID 32681029, 2020). "Encouragingly, we verified various well-known mechanistic changes associated with emphysema development, such as NF-κB signaling and TLR4 signaling, as well as increased levels of TNF-α, CSF2, and non-predicted but related interleukins, MPO, and MMP-9 by means of proteomic analysis." (PMID 25962837, 2015). "In addition, there were increased mRNA levels of TNF‐α, IL‐6, GCSF, macrophage inflammatory protein‐2 (MIP‐2), KC, and protein expression of nuclear factor kappa‐light‐chain‐enhancer of activated B cells (NF‐κB) in lung tissue and the destruction of airway spaces (a feature of emphysema)." (PMID 37119028, 2023). "Moreover, the mRNA expression of other representative proinflammatory mediators, including IL-1β, tumor necrosis factor-α (TNF-α), IL-8, IL-18, and immune modulators, such as interferon regulatory factor-5 (IRF-5) and transforming growth factor-β (TGF-β), was increased in emphysema mice." (PMID 32681029, 2020). "Furthermore, RLD significantly inhibited the expressions of IL‐1β, IL‐6, TNF‐α, and TGF‐β induced by cigarette smoke exposure, reduced the number of inflammatory cells in the bronchoalveolar lavage fluid, and alleviated the severity of cigarette smoke‐induced emphysema." (PMID 28749079, 2017). "After 4 months of exposure to CS, we observed significantly increased emphysema severity (MLI and DI) and elevation of pro-inflammatory factors (TNF-α and IL-1β) in serum without a significant change in BW." (PMID 34646841, 2021). "PLWH with emphysema had higher concentrations of TNFα, IL-1β and IL-6 than PLWH without emphysema." (PMID 33936110, 2021). "To test this hypothesis, we measured serum interleukine-6 (IL-6), tumor-necrosis factor (TNF), and C-reactive protein (CRP) in smokers with emphysema, smokers without emphysema, and in non smokers with normal lung function." (PMID 17822550, 2007). "PLWH with emphysema had higher concentrations of TNFα (median (IQR): 8.2 (6.4-9.8) versus 7.1 (5.7-8.6) pg/ml, p<0.001), IL-1β (median (IQR): 0.21 (0.1-0.4) versus 0.17 (0.1-0.3) pg/ml, p=0.004) and IL-6 (median (IQR): 3.6 (2.6-4.9) versus 3.1 (2.0-4.3) pg/ml, p=0.023) than PLWH without emphysema." (PMID 33936110, 2021).
acne (115 papers, 2009 to 2026). An inflammatory process of the sebaceous glands which is characterized by comedones, nodules, papules and/or pustules on the skin. "All these genes encode proinflammatory cytokines and chemokines previously detected in acne lesions and are linked to activation of the NF-κB pathway, inducing the upregulation of TNF-α, CXCL8/IL-8, IL-1β, CXCL1 and CXCL2." (PMID 35563458, 2022). "TNF-α is one of the factors expressed in the early stages of the inflammatory and immune reaction in acne and causes inflammatory responses such as vasodilatation, edema, and fever." (PMID 35269651, 2022). "Our results also shown that the associations between the skin microbiota composition and acne phenotypes, such as hyperkeratosis, IL-8 and TNF-α expression, were significantly related." (PMID 35211023, 2022). "Suppression of PI3K/Akt signaling inhibits lipogenesis induced by TNF-α, which is associated with acne development." (PMID 31281837, 2019). "The -308 G/A polymorphism in the tumor necrosis factor (TNF) gene has been implicated in the risk of acne vulgaris, but the results are inconclusive." (PMID 24498378, 2014). "A total of five publications evaluating the association between the TNF -308 G/A polymorphism and acne vulgaris risk were included in the meta-analysis, involving 1553 subjects (728 acne vulgaris cases and 825 controls)." (PMID 24498378, 2014). "This meta-analysis suggests that the -308 G/A polymorphism in the TNF gene contributes to acne vulgaris risk, especially in Caucasian populations." (PMID 24498378, 2014). "A number of case-control studies were conducted to investigate the association of -308 G/A polymorphism in the TNF gene and the risk of acne vulgaris." (PMID 24498378, 2014). "We were able to provide a more complete picture of the role of TNF -308 G/A polymorphisms in acne vulgaris risk, as comparing with that published in individual studies." (PMID 24498378, 2014). "Additionally, this process triggers macrophages to adopt an M1 phenotype and release pro-inflammatory cytokines (such as IL-1 and TNF-α), which play pivotal roles in acne-associated inflammatory responses." (PMID 38736879, 2024). "Moreover, the release of VEGF during TNF-α induction was also impaired, inhibiting another parameter associated with acne lesions." (PMID 35740016, 2022). "In acne pathogenesis, the increased activity of the virulence factor lipase caused by C. acnes overcolonisation led to an inflammatory response that resulted in the release of proinflammatory cytokines and TNF-α, which modulated host immune response." (PMID 36357775, 2022). "It is speculated that the acne-associated inflammation can in turn alter clock gene expression via the inflammatory cytokines such as TNF-α and IL-1β 29,30." (PMID 35414779, 2022). "The adipokine omentin may thus influence inflammatory processes that contribute to the pathogenesis of acne, such as by preventing inflammation caused by TNF." (PMID 33849530, 2021). "To date, several studies have been carried out to identify whether TNF -308 G/A polymorphism was associated with acne vulgaris risk." (PMID 24498378, 2014). "First, a relatively small number of studies were included and the sample sizes were still relatively small, which may not provide sufficient power to estimate the association between TNF -308 G/A polymorphism and acne vulgaris risk." (PMID 24498378, 2014). "Meta-analysis of the association between TNF -308 G/A polymorphism and acne vulgaris risk." (PMID 24498378, 2014). "TNF -308 G/A polymorphism might show significant association with the increased risk of acne vulgaris in all genetic models among Asian populations (all p<0.05), but not enough reliability was established due to the result from a single study." (PMID 24498378, 2014). "Therefore, we perform present meta-analysis to systematically clarify the association between the TNF -308 G/A polymorphism and acne vulgaris risk based on all eligible case-control studies." (PMID 24498378, 2014).
acne (continued). "Distribution of TNF -308 G/A polymorphism in acne patients and control subjects." (PMID 24498378, 2014). "However, further studies are still needed to warrant and validate the association between TNF -308 G/A gene polymorphism with acne vulgaris risk." (PMID 24498378, 2014). "The meta-analysis results showed that TNF -308 G/A polymorphism was linked to the risk of acne vulgaris under recessive and additive models ( AA vs. AG + GG: OR = 2.73, 95%CI: 1.37–5.44, p = 0.004; AA vs. GG: OR = 2.67, 95%CI: 1.28–5.57, p = 0.009; respectively)." (PMID 24498378, 2014). "Thus, P. acnes triggers the secretion of IL-1α, TNF-α, and the chemokine IL-8 which have been implicated in the inflammatory process of acne." (PMID 19629174, 2009). "Biologic agents, particularly TNF-α inhibitors such as adalimumab, have shown promise in isolated reports of severe acne and acne fulminans in adolescents and young adults." (PMID 41551620, 2026). "It highlights the potential utility of TNF-α inhibitors in rare, severe, and treatment-resistant pediatric acne." (PMID 41551620, 2026). "CPT contributes to reducing the levels of inflammatory cytokines IL-1β, IL-6, IL-8, and TNF-α in acne model rats." (PMID 40230697, 2025). "Excess lipid accumulation in ASCs and sebocytes stimulates the release of pro-inflammatory cytokines, such as TNF-α and IL-6, aggravating skin inflammation, promoting sebaceous gland activity, and exacerbating acne through mTOR signaling activation." (PMID 40227405, 2025). "Recent studies have also revealed potential in acne treatment, with Photodithazine® combined with micro-LED technology effectively reducing acne lesions and key inflammatory biomarkers such as interleukin-1α, IL-1β, tumor necrosis factor-α, and IL-8." (PMID 40869370, 2025). "Proinflammatory cytokines such as interleukin-1 (IL-1), IL-6, and tumor necrosis factor (TNF)-α, are known modulators of inflammatory responses in acne." (PMID 40851686, 2025). "In acne treatment, the production of IL-6 is regulated by IL-1β and TNF-α, which further amplifies the inflammatory cascade." (PMID 39942620, 2025). "AzA’s anti-inflammatory activity is mediated through the downregulation of pro-inflammatory cytokines, including interleukin-1 beta (IL-1β) and tumor necrosis factor-alpha (TNF-α), which are key drivers of inflammation in acne and rosacea pathophysiology." (PMID 41011144, 2025). "Borneol also effectively treats acne because of its anti-inflammatory and analgesic effects, and was found to inhibit acne-mediated production of IL-6, IL-1β, interleukin-8 (IL-8) and TNF-α by inhibiting the NFκB activation pathway." (PMID 41573729, 2025). "In acne pathogenesis, IL-1, IL-6, and tumor necrosis factor-alpha (TNF-α)—major inflammatory mediators—stimulate CRP production in the liver." (PMID 41465543, 2025). "Tanshinone can reduce the levels of IL-8, IL-6, IL-1β, and TNF-α in acne model rats, as profiled by lipidomics, with the mechanism possibly related to sphingolipid and glycerophospholipid metabolism pathways." (PMID 40230697, 2025). "In parallel investigations, CBD treatment at 10 μM within an LPS-induced acne-like context exhibited decreased levels of TNF-α, IL-1β, and IL-6." (PMID 38904694, 2024). "The closely linked factors are interleukins (IL-1β, IL-17, and IL-23) and tumor necrosis factor-alpha (TNF-α), offering new therapeutic targets for treating severe acne." (PMID 39403646, 2024). "Inflammation and cytokines, such as IL-1β, TNF-α, and IL-17, play pivotal roles in acne inflammation, underscoring the importance of regulating these cytokines as potential targets for acne treatments to mitigate inflammation and lesion formation." (PMID 38646359, 2024). "AF represents a unique and aggressive form of inflammatory acne with elevated inflammatory markers like TNF-alpha levels." (PMID 39139785, 2024). "Significantly increased levels of IL-1β (16-fold), TNF-α (2.6-fold), and IL-8 (3015-fold) were found in acne lesions compared to healthy skin." (PMID 39519131, 2024).
acne (continued). "Elevated IL-17, IL-23, and TNFα levels in acne lesions, coupled with TLR2(+) macrophages and IL-17 cells, reveal a complex network of inflammatory pathways that exacerbate acne severity." (PMID 38791344, 2024). "The binding of active androgens to AR can stimulate macrophages to secrete pro-inflammatory factors IL-1, IL-6, and TNF-α, which is consistent with the inflammatory response observed at acne lesion sites." (PMID 38736879, 2024). "Treatment of keratin-forming cells with glucocorticoids can increase the expression of TLR-2 receptors and increase the release of TNF-α and IL-1α, thus playing an important role in the formation of acne." (PMID 38585341, 2024). "This resulted in the alleviation of acne symptoms and a reduction in serum levels of TNF-α and IL-1β in rats." (PMID 38550588, 2024). "Its anti-inflammatory action includes reducing pro-inflammatory cytokines such as TNF-α and IL-6, while its antimicrobial properties help combat acne-related bacterial overgrowth." (PMID 39684852, 2024). "Agents targeting TNF-α, such as adalimumab and etanercept, have shown promise in treating aggressive forms of acne, including acne conglobata and fulminans." (PMID 38791344, 2024). "The molecular docking verification showed that the components were well bound to the core targets of acne, and the docking ability of stigmasterol and TNF (−12.73 kcal/mol) was particularly outstanding." (PMID 39029003, 2024). "In the study, it was observed that LCF can reduce hyperkeratosis and inhibit the inflammatory response in acne (reducing the expression level of IL-8 and TNF-α in serum and in the skin)." (PMID 39275081, 2024). "A significantly increased production of cytokines, including TNF-α, IL-1β, and granulocyte-macrophage colony-stimulating factor, characterizes this disorder with increasing amounts proportional to acne severity." (PMID 39063004, 2024). "The experimental results confirmed that GA inhibited lipid synthesis in vitro and in vivo, improved the symptoms of acne vulgaris, prevented mast cell infiltration and decreased the level of pro-inflammatory cytokines, including TNF-α, IL-1β and IL-6." (PMID 38792208, 2024). "In this study, the KEGG pathway was enriched, and it was found that the target proteins of PAD in the treatment of acne were mainly enriched in the TNF, AGE-RAGE, HIF-1 signaling pathway." (PMID 39029003, 2024). "As a result, the use of TNF-α inhibitors has been explored as a potential treatment for severe and refractory cases of acne." (PMID 39063004, 2024). "TNF-α, a pro-inflammatory cytokine, is involved in extensive inflammation in follicular skin diseases, such as acne, and also supports proliferation and sebum release of sebocytes." (PMID 37373478, 2023). "Upon stimulation by Propionibacterium acnes (P. acnes), the secretion of TNF-α and proinflammatory IL-8 is enhanced in peripheral blood mononuclear cells (PBMCs) of individuals with acne." (PMID 37894244, 2023). "To address the pathogenesis of acne vulgaris, we examined the expression of TNF-α, IL-1β in serum, and TLR2/NF-κB signaling pathway in tissues." (PMID 37159798, 2023). "L. rhamnosus significantly improved acne-like symptoms in rats by suppressing the level of inflammatory cytokines such as IL-1β, IL-6, and TNF-α." (PMID 38250060, 2023). "Subsequently, chemokines, including TNF-α, IL-8 and IL-6, were transcribed, which triggers inflammatory cell infiltration in acne skin." (PMID 35211023, 2022). "NF-κB increases the expression of pro-inflammatory factors including interleukin 1β (IL-1β), IL-6 and tumor necrosis factor alpha, three of which are essential in acne pathology." (PMID 35211023, 2022). "LCF can significantly (p < .05) inhibit the upregulated levels of IL-8 and TNF-α in rat skin with acne, thereby inhibiting the inflammatory response." (PMID 35211023, 2022). "Inflammatory markers such as IL-1, IL-6, IL-8, MMPs, and TNFα are the most relevant cytokines expressed in acne pathogenesis." (PMID 35910763, 2022).